BRAF (B-Raf proto-oncogene, serine/threonine kinase)
Diseases named in the same sentence as BRAF in open-access papers (continued):
Sharing a sentence is not in itself a finding about the gene and the disease.
melanoma (continued). "Activating mutations in N-RAS and BRAF proto-oncogenes in melanoma increase the glucose uptake by upregulation of glucose transportase-1 (GLUT1) and GLUT3 and enhanced glycolytic rates, as well as modifications of glutamine metabolism." (PMID 37762344, 2023). "Mutations in BRAF, specifically the V600E variant, are the most common genetic alterations in melanoma, occurring in approximately 50% of cases." (PMID 37760480, 2023). "Even though targeted therapy, including the combination of BRAF and MEK inhibitors, can yield a rapid response in melanoma with BRAF V600-activating mutations, almost all patients treated with targeted therapy develop resistance." (PMID 36647169, 2023). "MAPK pathway inhibitor (MAPKi) treatment significantly prolonged the survival of metastatic melanoma patients with BRAF V600 mutation (BRAFV600 mutant melanoma)." (PMID 37435085, 2023). "Very interestingly, it was described recently that 37% of melanoma patients who were positive for BRAF mutations were severely vitamin D-deficient (≤30 nmol/L) compared with 9% of BRAF wild-type patients." (PMID 37175742, 2023). "The B-Raf proto-oncogene, serine/threonine kinase (BRAF)/ mitogen-activated protein kinase kinase (MEK) targeting agents have become the treatment of choice for BRAF-mutated melanoma during the last decade." (PMID 38222175, 2023). "In this real‐world study, melanoma patients with BRAF, KIT, or NRAS mutations treated with anti‐PD‐1 adjuvant monotherapy had no statistical difference of DFS compared to patients received IFN or observation." (PMID 37403699, 2023). "The BRAF inhibitors show effects on approximately half of melanoma patients with BRAF mutation, but a majority of patients develop secondary resistance within a relatively short time." (PMID 37404751, 2023). "Activating point mutations of the BRAF gene encoding the serine/threonine-protein kinase BRAF have been identified in 50–60% of malignant melanomas, and at similar or lower frequencies in several other cancers." (PMID 37219686, 2023). "Some of these transcription factors are regulated by cAMP signaling and are implicated in BRAF-mutant MEK inhibitor-resistant melanomas." (PMID 36765834, 2023). "In melanoma patients, the most common oncogenic mutation is the BRAF-V600E mutation, which occurs in up to 50% of metastatic melanomas, and these patients should be treated with targeted therapies." (PMID 37627116, 2023). "We have shown short-term better control of melanoma relapses when RAF/MEKi were used in patients with BRAF-mutated melanomas; however, beyond 2 years, long-term outcomes overlap with immunotherapy with anti-PD1 antibodies." (PMID 37686659, 2023). "Among them, BRAF V600E mutation accounts for the majority (80–90%) of all BRAF mutations in melanoma." (PMID 36982192, 2023). "KRAS and BRAF mutations are other two mutations widely assessed in various cancer types, including pancreatic cancer, colon cancer, and melanoma." (PMID 37849806, 2023). "We aimed to study for the first time the anti-tumor activity of GP-2250 in BRAF-mutated melanoma cell lines and benign melanocytes, also addressing the expression of parts of the PI3K/AKT/mTOR signaling pathway." (PMID 37895015, 2023). "Although BRAF inhibitors have been broadly effective in treating melanoma patients who have the BRAF V600E mutation, a much smaller portion of BRAF-mutated patients with other cancer types, such as colorectal cancer (CRC), respond to the same treatment." (PMID 38136350, 2023). "The Cancer Genome Atlas Network has divided melanoma mutations into four sub-types being BRAF, RAS, NF-1, and triple-wild type." (PMID 36865793, 2023). "In the melanoma group, 4 of 10 patients had a BRAF V600E mutation, 2 were stage IIIA, 2 were stage IIIB, 1 was stage IIID and 5 were stage IV at the time of initiating ICIs." (PMID 37671166, 2023). "Activating mutations in the NRAS and BRAF genes play an important role in promoting the progression of melanoma." (PMID 37221594, 2023).
melanoma (continued). "Targeted therapies (TT) against BRAF mutated melanoma and immune checkpoints blockade therapies (ICB) have been a breakthrough in the treatment of metastatic melanoma." (PMID 36774337, 2023). "BRAF somatic missense mutation where a valine amino acid is substituted for glutamic acid at exon 6 (V600E) is identified to occur in 50% of melanoma cases." (PMID 36967556, 2023). "Taken together, we propose that patients with treatment-naïve BRAF-mutated melanoma would benefit from a combination treatment with BRAFi and PARPi as resistance quickly develops in the majority of MAPKi single treated patients." (PMID 37674529, 2023). "In this study, public databases were exploited to explore a potential therapeutic target for BRAF-mutated melanoma." (PMID 37745303, 2023). "This distinct glycolytic phenotype in BRAF-mutated melanomas is triggered by mutations in NRAS and BRAF." (PMID 37627054, 2023). "Patients who underwent radical surgery and were diagnosed as Stage III melanoma harboring BRAF V600 mutation by pathological report were retrospectively identified at Fudan University Shanghai Cancer Center from January 2017 to December 2021." (PMID 37016119, 2023). "Although the advent of an immune checkpoint inhibitor (ICI) and targeted therapy have dramatically improved the outcomes of advanced melanoma, BRAF-mutated patients continue to have a poor prognosis." (PMID 36995534, 2023). "And thus, melanoma patients will benefit from a better understanding of immune phenotypes connected to BRAF mutation, resulting in better therapy and improved outcomes." (PMID 37205993, 2023). "The novel encorafenib and binimetinib combination, already approved for BRAF-mutated melanoma, has been investigated in two different phase II trials (ENCO-BRAF, OCEANII) for NSCLC patients." (PMID 37894445, 2023). "Two studies showed intratumoral heterogeneity within the same melanoma samples for BRAF and TERT mutation status using different micro-dissected regions of the same sample." (PMID 38003476, 2023). "The multifaceted role of miR-579-3p in melanoma has been focused on a novel oncosuppressive miRNA previously identified as a master regulator of resistance to targeted therapies in BRAF-mutated melanomas." (PMID 37507791, 2023). "The V600E BRAF mutation is common in melanomas and is the target for the specific chemotherapy of melanoma." (PMID 37444590, 2023). "Following DNA sequencing, a BRAF V600K mutation was revealed, thus confirming the diagnosis of dedifferentiated melanoma with atypical fibroxanthoma features." (PMID 37373134, 2023). "We found that TMB and BRAF mutation status are independent predictive factors for RFS of stage III/IV melanoma patients with adjuvant PD-1 antibody therapy." (PMID 35192052, 2023). "BRAF V600 mutation is the most common oncogenic alternation in melanoma and is visible in around 50% of cutaneous and 10%–15% of acral or mucosal subtypes." (PMID 37016119, 2023). "The selective BRAF inhibitor Vemurafenib is an oral small molecule approved by FDA in 2011 and the first successful therapy targeting BRAF-mutated melanoma." (PMID 37417899, 2023). "Some studies report a more aggressive clinical course in BRAF mutated melanoma and a worse outcome compared to BRAF-wildtype melanoma." (PMID 35192052, 2023). "The effect of the seed extracts and vemurafenib on the expression of BRAFWT and BRAFV600E genes in the melanoma cells were evaluated to detect BRAF mutation specific genomic changes." (PMID 36678596, 2023). "In a study investigating the genomic profile of 122 acral melanomas using DNA sequencing, mutations in BRAF (21.3%), NRAS (27.9%), and KIT (11.5%) were identified." (PMID 36980308, 2023). "Vemurafenib, a selective BRAF inhibitor approved for treatment of BRAF-mutated melanoma, was in fact the first BRAF-inhibitor studied in DTC." (PMID 37435488, 2023).
melanoma (continued). "Mutation at V600E in the BRAF gene (BRAFV600E mutation) in melanoma cells can promote glycolysis to absorb and integrate substances required for tumour cell proliferation." (PMID 37221594, 2023). "It has been described in 4% of mutated BRAF melanomas and plays a significant role in developing BRAFi resistance." (PMID 37958416, 2023). "Mutation in this gene is present in 7% of all tumors, with the majority being melanomas, where BRAF mutation is observed in up to 50%." (PMID 37958416, 2023). "Anti-tumoral activity was observed among melanoma patients with BRAF mutations, with 8 of 53 (15.1%) achieving PR and 27 of 53 patients with stable disease." (PMID 37370834, 2023). "Trametinib is a highly selective allosteric mitogen-activated protein kinase kinase (MEK) inhibitor, that was originally approved for the treatment of malignant melanoma driven by the BRAF V600E mutation in combination with BRAF inhibitors, such as dabrafenib." (PMID 36982163, 2023). "When ER stress is inhibited using the induction of chemical chaperones, autophagic activity is reduced and apoptosis increases in the BRAF-mutated melanoma." (PMID 37601686, 2023). "In this cohort study of 94 patients with resected melanoma brain metastases that underwent targeted DNA sequencing, BRAF V600E variant lesions were associated with worse intracranial progression-free survival and overall survival." (PMID 37589977, 2023). "Concerning BRAF-mutated melanoma with low TILs, the optimal therapeutic strategy should be sought, as BRAF inhibition can have immunomodulatory effects by increasing the number of TILs or reprogramming them." (PMID 37295047, 2023). "Using gene expression analysis and mass spectrometry-based lipidomics of BRAF-mutant melanoma cell lines, melanoma PDX and clinical data sets, we explored the association of FASN expression with membrane lipid poly-unsaturation and therapy-resistance." (PMID 37072838, 2023). "The first turning point in the therapeutical approach for melanoma was the discovery of activating BRAF mutation." (PMID 36831607, 2023). "Somatic mutations of BRAF have been associated with various malignancies including malignant melanoma, thyroid, lung, ovarian and colorectal cancers." (PMID 37697378, 2023). "In a large cohort of mucosal melanomas, 3% of AMs showed BRAF, 10% showed NRAS, and 19% showed KIT mutations." (PMID 35642348, 2023). "Vemurafenib and dabrafenib are BRAF kinase inhibitors (BRAFi) used for the treatment of patients with melanoma carrying the V600E BRAF mutation." (PMID 36765875, 2023). "Next, RT-qPCR analysis was performed on A2058-upGALC vs. A2058-mock cells to assess the expression levels of genes encoding for various proteins up- or downregulated by GALC overexpression in BRAF-mutated melanoma cells." (PMID 37445731, 2023). "BRIM-8 is a phase three randomized controlled trial which randomized patients with resected high-risk BRAF-mutant melanoma to receive vemurafenib vs. placebo." (PMID 36836846, 2023). "Approximately 50–70% of melanoma patients harbor cancer driving mutations in the BRAF gene, making it a powerful therapeutic target in melanoma treatment." (PMID 37235843, 2023). "Activating mutations of BRAF mutations are present in ~50% of all melanoma cases and involve a substitution of the valine at position 600 (V600)." (PMID 37372043, 2023). "This study provides seven additional examples of patients with pediatric melanoma who underwent BRAF testing, yet more research is necessary to determine the influence of BRAF mutations on pediatric melanoma outcomes." (PMID 38136349, 2023). "A375 cells contain the BRAF V600E mutation, which is the most frequently occurring mutation in human melanoma." (PMID 37114375, 2023).
melanoma (continued). "In a melanoma with BRAF mutation, slow‐cycling persister cells display an increased level of mitochondrial oxidative‐ATP‐synthetic gene expression after treatment as well as improve their susceptibility to mitochondrial respiratory chain inhibition." (PMID 37638338, 2023). "Here, we examined in vitro how Nox-derived ROS in BRAF-mutated melanoma cells regulates their drug sensitivity and metastatic potential." (PMID 37189846, 2023). "The exploration of effective therapy for non-V600 BRAF mutations in melanoma has thus attracted much interest." (PMID 36686670, 2023). "Our model suggests a possible role of mitochondrial dysfunction/stress and the rewiring of mitochondrial energy hemostasis (a well-known hallmark of cancer cells) in the emergence of BRAF inhibitor resistance in melanoma." (PMID 37176114, 2023). "The addition of trametinib has been reported to improve OS compared to dabrafenib alone in patients with BRAF Val600 mutation-positive melanoma." (PMID 36983983, 2023). "In patients with BRAF-mutated melanoma, another evaluated option is represented by the association of ICIs and target therapy." (PMID 38201531, 2023). "Although both BRAF V600E and V600K mutant melanoma benefit from BRAFi, melanomas with BRAF V600K mutations have shorter progression-free survival under BRAF inhibitors but superior response to immune checkpoint inhibitors compared to V600E mutants." (PMID 37239381, 2023). "Several human cancers, including melanoma and colorectal carcinoma, harbor a specific mutation within the BRAF gene, termed V600E." (PMID 37079639, 2023). "Targeted treatment for patients with BRAF melanoma has reversed the poor prognosis associated with this molecular alteration." (PMID 36998456, 2023). "For example, skin cutaneous melanoma cell lines (SKCM) harbouring BRAF V600E mutations are vulnerable to BRAF kinase inhibitors, and furthermore, this in vitro observation generalises to in vivo models and melanoma patients." (PMID 37558831, 2023). "It has been demonstrated also that therapeutic strategies targeting EZH2 or its downstream targets, such as the ciliary-related oncogene PLK1, in combination with BRAF inhibitors are potential novel therapeutic options in melanomas with BRAF mutations." (PMID 37510333, 2023). "Following the outcomes of the COMBI-AD clinical trial (NCT01682083), dabrafenib-plus-trametinib received FDA approval in 2018 as an adjuvant treatment for melanoma patients harboring BRAF V600E or V600K mutations." (PMID 38139110, 2023). "Previous studies in BRAF mutated melanoma have demonstrated that stromal fibroblast mediated compensatory activation of the AKT pathway leads to reduced efficacy of BRAF inhibitors." (PMID 36952536, 2023). "Molecular targeted therapy with BRAF inhibitor has been approved to treat BRAFV600E-mutated melanoma." (PMID 37658191, 2023). "RSK phosphorylates PFKFB2 to increase PFKFB2 activity and the glycolysis pathway, which accelerates the growth of BRAF‐mutated melanoma." (PMID 37143582, 2023). "The aim of this manuscript is to review the role of BRAF mutational status in the pathogenesis of melanoma and its impact on differentiation and inflammation." (PMID 37627054, 2023). "The BRAF gene mutations cause uncontrolled cell division of the melanocytes and the development of melanoma." (PMID 36676131, 2023). "In melanoma, the presence of the BRAF V600E mutation correlates with certain histopathologic features, including intraepidermal upward scatter of melanocytes, nest formation of intraepidermal melanocytes, thickening of the epidermis, and larger tumor cells." (PMID 37156689, 2023).
melanoma (continued). "The peaks corresponding to m/z 944.4, 1825.9, and 2169 were identified as the main discriminating factors for BRAF mutated versus NRAS mutated malignant melanoma (MM)." (PMID 36982192, 2023). "Due to the relatively high frequency of BRAF mutations in melanoma, several targeted treatments have been developed." (PMID 36865793, 2023). "The preliminary data of the present study indicate that GP-2250 has anti-neoplastic effects in BRAF-mutated melanoma cell lines regarding tumor cell viability, proliferation, and apoptosis/necrosis." (PMID 37895015, 2023). "Previous genomic classification of melanoma patient based on the pattern of the most prevalent significantly mutated genes leads to four subtypes, including mutant BRAF, mutant RAS, mutant NF1, and Triple-WT (wild-type)." (PMID 37904237, 2023). "Here, we extend these observations and demonstrate that GALC overexpression plays a pro-tumorigenic function on both A2058 and A375 human melanoma cells that harbor the BRAF(V600E)-activating mutation, which is present in approximately 50% of human melanomas." (PMID 37445731, 2023). "This supports previous studies establishing an association of IFN receptor levels with the antiproliferative efficacy of IFN in HCC, and is in line with reports on IFNAR downregulation in advancing bladder cancers, and also BRAF-mutated melanoma." (PMID 38066598, 2023). "As a reminder, this RCT tested the optimal sequence of TT and ICI treatments for patients with advanced melanoma harboring a V600 BRAF mutation." (PMID 37025593, 2023). "Cobimetinib and trametinib are two recently approved MEK inhibitors for advanced melanoma and pediatric patients with low-grade glioma bearing a BRAF V600E mutation, respectively." (PMID 37631380, 2023). "Targeting of MAP kinase pathways by BRAF inhibitors has evolved as a key therapy for BRAF-mutated melanoma." (PMID 36902392, 2023). "This is epitomized by the application of ErbB2‐targeted drugs in a subset of breast cancers, of BRAF inhibitors in melanomas, of drugs targeting liabilities due to mutated BRCA in gynecological tumors, to cite some key examples." (PMID 36722641, 2023). "We therefore employed the YUMMER1.7 melanoma cell line, which has a mutation in BRAF and loss of PTEN and CDKN2A along with additional radiation-induced mutations." (PMID 36821392, 2023). "On study demonstrated that melanoma cells with MITF amplification were more resistant to BRAF inhibition, while cells with MITF loss were more sensitive." (PMID 37504268, 2023). "BRAF mutation is the most frequent genetic alteration in melanomas, comprising around 50% of the cases." (PMID 37174717, 2023). "Roughly 50% of melanomas harbor a BRAF mutation, especially the variant V600E, suitable for targeted therapy with BRAF inhibitors." (PMID 37568570, 2023). "In total, 16 of them had BRAF V600-mutated melanoma and had been previously treated with vemurafenib or dabrafenib." (PMID 36995534, 2023). "Picard and colleagues also showed a significant difference in overall survival between the BRAF-mutated and wild-type patients in a study with 72 melanoma patients after positive sentinel node dissection." (PMID 35192052, 2023). "To study the effect of TERT inhibition on BRAF-mutated melanoma cells in culture, we treated sensitive and resistant cells with 6-thio-dG alone or in combination with vemurafenib and analyzed the effect on cellular proliferation." (PMID 37296851, 2023). "Currently, systemic therapies approved as adjuvant therapy for melanoma include pembrolizumab, ipilimumab, and nivolumab as well as dabrafenib plus trametinib for patients with a BRAF V600 mutation." (PMID 36816935, 2023). "In patients with melanoma BM, either immunotherapy or BRAF and MEK inhibitors have been associated with high brain control and survival benefit." (PMID 37016421, 2023).